ACE (angiotensin I converting enzyme)
Diseases named in the same sentence as ACE in open-access papers (continued):
Sharing a sentence is not in itself a finding about the gene and the disease.
congestive heart failure (258 papers, 2005 to 2026). Failure of the heart to pump a sufficient amount of blood to meet the needs of the body tissues, resulting in tissue congestion and edema. "Myocardial PKC stimulation also leads to angiotensin-converting enzyme (ACE) gene upregulation This is believed to be one of the causes of congestive heart failure due to cardiomyocytes’ hypertrophy and cardiac fibrosis triggered by ACE induction." (PMID 38892303, 2024). "Others reported the risk of hyperkalemia to be greater in ACE inhibitor patients who have congestive heart failure, especially if they also consume potassium supplements or potassium-rich foods." (PMID 29558445, 2018). "In patients with cachexia related to congestive heart failure, treatment with ACE inhibitors caused an increase in both subcutaneous fat and muscle mass." (PMID 26856534, 2016). "For instance, ACE inhibitor and beta-blocker therapy after acute MI complicated by congestive heart failure or LV dysfunction has demonstrated a 15–20% relative risk reduction in mortality and cardiovascular morbidity within stable patients." (PMID 20730096, 2010). "Hence, as recommended from the 2021 ESC Guidelines for the diagnosis and treatment of acute and chronic heart failure, sac/val is recommended as a replacement for an ACE-inhibitor in patients with HFrEF to reduce the risk of HF hospitalization and death." (PMID 38004547, 2023). "In eight infants with congestive heart failure, a similar mean inhibition of ACE activity of 75.5% was observed after four hours, but after a single dose of 0.25 mg/kg enalapril maleate." (PMID 41155980, 2025). "Anti-congestive heart failure (HF) treatment by diuretics (loop diuretics, thiazide, and aldosterone antagonists) and vasodilators (angiotensin-converting enzyme [ACE] inhibitors) was optimized." (PMID 39742192, 2024). "The di- or tripeptides derived from YML possess antioxidant activity and also trigger angiotensin I-converting enzyme (ACE) inhibitors, a class of medicine used for chronic heart failure in animals and human." (PMID 38042833, 2023). "Concisely, current evidence demonstrates the benefits of using combinations of high-dose ACE inhibitors, β-blockers, and diuretics in significantly reducing death and disability when compared to conventional therapy for patients with congestive heart failure." (PMID 36348831, 2022). "Both drugs are ACE inhibitors that are the first line of treatment for chronic heart failure although a substitute combination is being sought in this study." (PMID 36141396, 2022). "Congestive heart failure therapy with diuretics, ACE inhibitors and beta blockers are commonly used." (PMID 33078963, 2021). "Therapy for chronic heart failure was then started (ACE inhibitors, betablockers, mineralocorticoid receptor antagonist)." (PMID 34202524, 2021). "The central significance of ACE-inhibitors in treatment of chronic heart failure has been highlighted in several randomized controlled trials." (PMID 33320290, 2021). "Various clinical trials have shown that for patients with congestive heart failure, enalapril or related angiotensin-converting enzyme (ACE) inhibitor can reduce its mortality and morbidity." (PMID 34901931, 2021). "ACE inhibitors are a class of antihypertensive drugs, which is primarily used for the treatment of cardiovascular (e.g., congestive heart failure (CHF)), or renal diseases." (PMID 33776749, 2020). "Echocardiography analyses revealed that the proband had shown early onset congestive heart failure, which is managed with a treatment regime including ACE and aldosterone inhibitors." (PMID 33304277, 2020). "Angiotensin-converting enzyme (ACE) inhibitors (ACEi) remain important drugs for the treatment of congestive heart failure." (PMID 31297545, 2019). "Methyldigoxin was often replaced by beta-blockers and/or ACE inhibitors in patients with chronic heart failure, which is also in line with clinical guidelines." (PMID 30760276, 2019).
congestive heart failure (continued). "Patients with chronic heart failure that have been treated with ACE inhibitors had reduced fibrinogen and endothelial von Willebrand factor levels when compared with baseline." (PMID 29545754, 2018). "Due to its ability to mitigate adverse myocardial remodeling, ACE inhibition has become the standard of care for patients with congestive heart failure." (PMID 29282149, 2017). "This is the first network meta-analysis to compare the efficacy and safety of ACE inhibitors in patients with chronic heart failure (NYHA II or III)." (PMID 26871774, 2016). "Aggressive nutritional support and replacement of selenium and congestive heart failure medications that included diuretics and ACE inhibitors with the addition of carvedilol led to normalization of the cardiac function within four weeks." (PMID 27994905, 2016). "The ValHeFT study analyzed the benefits of the addition of valsartan to ACE inhibitor in 3034 chronic heart failure (CHF) patients." (PMID 23136031, 2013). "ACE inhibitors are also routinely used in treatment of congestive heart failure of pediatric DCM patients." (PMID 23213342, 2012). "Several therapeutic approaches in congestive heart failure management have led to an important reduction of cardiovascular morbidity and mortality like the blockade of the renin-angiotensin system by angiotensin-converting enzyme (ACE) inhibitors." (PMID 20376345, 2010). "Number of events in randomized controlled trials comparing combination therapy with angiotensin II receptor antagonists and angiotensin-converting enzyme inhibitor therapy versus ACE inhibitor alone in patients with congestive heart failure." (PMID 20376345, 2010). "Co-medication in randomized controlled trials comparing combination therapy with angiotensin II receptor antagonists and angiotensin-converting enzyme inhibitor therapy versus ACE inhibitor therapy alone in patients with congestive heart failure." (PMID 20376345, 2010). "Trial characteristics of randomized controlled trials comparing combination therapy with angiotensin II receptor antagonists and ACE inhibitor therapy versus ACE inhibitor therapy alone in patients with congestive heart failure." (PMID 20376345, 2010). "A recent study has demonstrated that in patients with chronic heart failure, long-term therapy with ACE inhibitors improved respiratory muscle strength." (PMID 20462446, 2010). "Baseline characteristics of patients enrolled in randomized controlled trials comparing combination therapy with angiotensin II receptor antagonists and ACE inhibitor therapy versus ACE inhibitor therapy alone in patients with congestive heart failure." (PMID 20376345, 2010). "Our study is based on trials retrieved from an extensive literature search to identify all relevant eligible trials comparing combination of ARB plus ACE inhibitor therapy to ACE inhibitor therapy alone in patients with congestive heart failure." (PMID 20376345, 2010). "Data on the cost-effectiveness of combination therapy compared to ACE inhibitor therapy alone for the treatment of congestive heart failure are scarce." (PMID 20376345, 2010). "The circulating RAS is known to exert pro-inflammatory and pro-fibrotic effects on the heart, whereas ACE inhibitors reduce mortality rates in patients with congestive heart failure." (PMID 18782187, 2008). "Given its dual action, sampatrilat may offer more excellent benefits in treating chronic heart failure than traditional ACE inhibitors." (PMID 39764460, 2024). "On the contrary, a modulation of the RAAS by ACE inhibitor therapy induced an increase in Treg cells and decreases in the Th1/Th2 cytokine ratio and pro-inflammatory cytokine secretion in patients with chronic heart failure." (PMID 35878343, 2022). "In the treatment of chronic heart failure, Sampatrilat could potentially provide a greater benefit than traditional ACE inhibitors." (PMID 32013233, 2020).
congestive heart failure (continued). "ACE inhibitors are particularly administered to patients presenting signs of congestive heart failure; our data may indicate a higher prevalence of this condition among patients having deceased." (PMID 27553421, 2016). "The individual START criterion yielding most scores was omission of an ACE inhibitor for patients with chronic heart failure (intervention group: 15 points on admission and 4 points at discharge; control group: 20 points on admission and 26 points at discharge)." (PMID 25364817, 2014). "In the non-CKD population with congestive heart failure (CHF), evidence from randomized trials suggests that treatment with certain medications including ACE inhibitors, angiotensin receptor blockers and β-blockers reduces morbidity and mortality in congestive heart failure (CHF)." (PMID 23849306, 2013). "A recent study suggested that both AGS-IV and the ACE inhibitor quinapril could improve cardiac function in a rat model of chronic heart failure." (PMID 23028693, 2012). "The addition of ARB to background therapy with ACE inhibitors has an additional attenuating effect on LV remodeling, and thus offers the potential to reduce cardiovascular morbidity and mortality in patients with congestive heart failure." (PMID 20376345, 2010). "Characteristics of 137 chronic heart failure patients based on the use of an ACE inhibitor." (PMID 19318756, 2009). "The aim of the study was to determine the impact of selected angiotensin converting enzyme (ACE) and PDE5A polymorphisms on presence of congestive heart failure (CHF) due to MMVD in Cavalier King Charles Spaniels (CKCS)." (PMID 38053473, 2023). "There are some known risk factors that may predispose patients with SGLT2i treatment to AKI, like decreased blood volume, chronic kidney insufficiency, congestive heart failure, and concomitant medications such as diuretics, ACE inhibitors, ARBs, and NSAIDs (U.S. Food and Drug Administration, 2016)." (PMID 36003521, 2022). "Early identification of cardiac dysfunction is important, as further LVEF reductions or development of congestive heart failure may be prevented by cardio-protective treatment with beta-blockers and/or angiotensin converting enzyme (ACE) inhibitors, or by timely interruption of trastuzumab." (PMID 34753503, 2021). "In cachectic patients with Congestive Heart Failure (CHF), combination therapy of the angiotensin-converting enzyme (ACE) inhibitor “enalapril”, Digoxin and diuretic increase subcutaneous fat and muscle bulk together with a significant raise in plasma albumin." (PMID 32102506, 2020). "Early detection of left ventricular systolic dysfunction is important, since early treatment with ACE inhibitors has been shown to delay the progression toward overt congestive heart failure (CHF) and to prolong life." (PMID 18298821, 2008). "For example, MoviPrep is contraindicated in patients with electrolyte imbalances, congestive heart failure, or those taking diuretics or ACE (angiotensin-converting enzyme) inhibitors." (PMID 40416163, 2025). "Both β-AR blocking agents and/or angiotensin-converting enzyme (ACE) inhibitors significantly improve survival rates for patients with chronic heart failure." (PMID 33590335, 2021). "Unless contraindicated, angiotensin-converting enzyme (ACE) inhibitors and beta blockers are indicated in symptomatic congestive heart failure." (PMID 32121065, 2020). "RAAS inhibitors (angiotensin-converting enzyme (ACE) inhibitors, angiotensin (AT) receptor blockers and aldosterone receptor antagonists) are well-established standard treatments for chronic heart failure." (PMID 30443826, 2018). "Furthermore, high-dose aspirin may also attenuate the benefit of angiotensin-converting enzyme (ACE) inhibitors in hypertensive and congestive heart failure patients because aspirin may attenuate the synthesis of PGE3 and PGI2, which is promoted by ACE inhibitors." (PMID 22195280, 2012).
congestive heart failure (continued). "According to current guidelines, the use of beta-blockers, ACE inhibitors, AT-II receptor blockers, aldosterone antagonists, diuretics, sacubitril-valsartan, and SGLT-II inhibitors belong to the first-line treatment strategies in chronic heart failure." (PMID 38248718, 2023). "This is supported by the absence of correlation between aldosterone and AngII levels in congestive heart failure patients treated with an ACE inhibitor, in which elevations in aldosterone were not necessarily accompanied by changes in AngII." (PMID 22017794, 2011). "Furthermore, the balance between angiotensin-converting enzyme (ACE) and its homolog ACE2 or between AT1 and angiotensin II type 2 receptor in the brain may be an important determinant of sympathoexcitation in chronic heart failure." (PMID 22919539, 2012). "In contrast, the other four trials did not report recommended fixed target doses of ACE inhibitor therapy, although in one trial clinicians were advised to target the doses of ACE inhibitors known to reduce morbidity and mortality in patients with congestive heart failure." (PMID 20376345, 2010). "Indeed, the treatment of older people without congestive heart failure (CHF) with angiotensin I converting enzyme (ACE) inhibitors improves physical performance." (PMID 30984113, 2019).
Obesity (234 papers, 2005 to 2026). Accumulation of substantial excess body fat. "Fas cell surface death receptor (Fas), versican (Vcan), T-box transcription factor 21 (Tbx21), angiotensin I converting enzyme (Ace), and serpin family E member 2 (Serpine2), metabolic markers associated with obesity, were increased in the obese group." (PMID 38728395, 2024). "Thirdly, obesity-related comorbidities such as heart, kidney, and pancreatic diseases can contribute to dysregulation of the ACE/ACE2 axis in tissue associated with these diseases." (PMID 37763674, 2023). "It is a hallmark of obesity-related CKD that ACE–Ang II activation in the kidney leads to renal ectopic lipid deposition." (PMID 36793875, 2023). "Overall, these data indicate that inhibiting renal hyperfiltration with an ACE inhibitor is advantageous in preventing the early development of glomerular injury and renal inflammation associated with obesity." (PMID 34975523, 2021). "In hypertensive patients with overweightness or obesity, ACE inhibitor treatment was associated with a reduction in markers of endothelial dysfunction." (PMID 33800427, 2021). "Circulating levels of ACE are influenced by the genetic polymorphism known to be related to obesity." (PMID 32121233, 2020). "Contrary to this findings, previous studies have shown a positive association between ACE I/D polymorphism and obesity, as the D allele of the ACE gene is frequently detected in younger obese men including preschool children, children and adolescents." (PMID 32408411, 2020). "The present study is the first to investigate the association between the ACE I/D polymorphism and susceptibility for overweight/obesity of healthy Korean adults." (PMID 32408411, 2020). "The association between ACE and obesity has been suggested to be the result of the role of angiotensin II in the development of adipose tissue." (PMID 32121233, 2020). "ACE gene polymorphisms have also been linked with increases in BMI and incidence of obesity in clinical populations." (PMID 31262355, 2019). "So, we explored the relationship between ACE gene I/D polymorphism and obesity based on BMI multiclassification." (PMID 28115791, 2016). "In conclusion, the relationship of ACE gene I/D polymorphism with obesity is insignificant in Chinese patients with T2DM." (PMID 28115791, 2016). "In the current study on Egyptian females, the association of ACE I/D polymorphism with obesity and several related disorders was studied." (PMID 27777603, 2016). "Association between the ACE polymorphism and the BMI-defined overweight and obesity was insignificant based on our analysis." (PMID 28115791, 2016). "We found that there was no statistical significance in the relationship of ACE gene I/D polymorphism with BMI-based obesity, whereas ACE II carriers showed higher SBP and PP than those of DD and ID carriers." (PMID 28115791, 2016). "Association between ACE gene I/D polymorphism and the risk of overweight/obesity remains controversial." (PMID 28115791, 2016). "The relationship of ACE gene I/D polymorphism with obesity was insignificant in Chinese patients with T2DM." (PMID 28115791, 2016). "Our previous study found that the association between the ACE I/D polymorphism and obesity in relation to sodium intake is gender-dependent in children." (PMID 25768006, 2015). "The genetic polymorphisms in this gene, which highly influence the ACE circulating level, have been repeatedly found to be associated with measures of obesity." (PMID 21340022, 2011). "There were significant positive associations with severe depression, obesity and use of ACE inhibitors." (PMID 20003540, 2009). "Altered levels of ACE caused by obesity have been previously suggested as a potential pathway through which obesity leads to the elevation of BP in adults." (PMID 19291311, 2009).